ZFP28 (ZFP28 zinc finger protein)
Description:
May be involved in transcriptional regulation. May have a role in embryonic development.
Synonyms: KIAA1431; mkr5
Tractability: PROTAC: ubiquitination databases record sites on it.
Gene: Protein-coding gene on chromosome 19 (56,538,948 to 56,556,808, forward strand). Ensembl gene ENSG00000196867.
Subcellular location: Nucleus
Subcellular location (Human Protein Atlas): Nucleoplasm; Cytosol
Pathways (Reactome):
Gene expression (Transcription): Generic Transcription Pathway
Gene Ontology:
Molecular function: DNA-binding transcription factor activity, RNA polymerase II-specific; RNA polymerase II cis-regulatory region sequence-specific DNA binding
Biological process: regulation of transcription by RNA polymerase II; regulation of DNA-templated transcription
Cellular component: nucleus; nucleoplasm
Genetic constraint (gnomAD): Loss-of-function variants: 31 observed, 39.64 expected, observed/expected ratio (o/e) 0.78, 90% interval 0.59 to 1.06. The upper end of that interval is the gene's LOEUF score, 1.06, which puts it in group 4 of 6, group 1 being the genes least tolerant of losing a copy. Missense variants: 924 observed, 1,063.8 expected, observed/expected ratio (o/e) 0.87, 90% interval 0.82 to 0.92. Synonymous variants: 400 observed, 383.74 expected, observed/expected ratio (o/e) 1.04, 90% interval 0.96 to 1.13.
Homologues: Orthologues: chimpanzee ZFP28 (99% identical), macaque ZFP28 (96% identical), dog ZFP28 (85% identical), pig ZFP28 (80% identical), rabbit ZFP28 (80% identical), rat Zfp28 (73% identical), mouse Zfp28 (72% identical), guinea pig ZFP28 (71% identical). Paralogues in human: ZNF470 (46% identical), ZNF471 (42% identical), ZNF197 (35% identical), ZNF33B (35% identical), ZNF41 (34% identical), ZNF585B (34% identical), ZNF658 (34% identical), ZNF568 (33% identical), ZNF28 (33% identical), ZNF254 (33% identical), ZNF841 (33% identical), ZNF726 (32% identical), and 164 more.
Diseases named in the same sentence as ZFP28 in open-access papers:
ZFP28 is named in the same sentence as 7 diseases in open-access papers, as found by Europe PMC text mining. Sharing a sentence is not in itself a finding about the gene and the disease. The quoted sentences say what the papers report.
colorectal cancer (1 paper, 2022). A primary or metastatic malignant neoplasm that affects the colon or rectum. "In contrast, ZNF880 and ZFP28 were found upregulated in colorectal cancer and melanoma, respectively." (PMID 36547193, 2022).
lung adenocarcinoma (1 paper, 2019). A carcinoma that arises from the lung and is characterized by the presence of malignant glandular epithelial cells. "In lung adenocarcinoma of current smokers, genome-wide significant CpGs annotated to multiple small nucleolar RNA genes, ribosomal subunit genes (RSPs), myosin immunoglobulin (MYO1G), and zinc finger protein 28 (ZFP28)." (PMID 30872662, 2019).
Patent ductus arteriosus (1 paper, 2021). In utero, the ductus arteriosus (DA) serves to divert ventricular output away from the lungs and toward the placenta by connecting the main pulmonary artery to the descending aorta. "PRDM6 is associated with isolated nonsyndromic patent ductus arteriosus, while ZFP28 plays an essential role in controlling gene expression during cardiac and vascular pathogeneses." (PMID 33466592, 2021).
tumor (2 papers, 2020 to 2022). "BSP was performed focusing on the promoter regions of four potential PMDGs (DPP6, HIST1H4E, MTMR7, and ZFP28) in 72 paired tumor and adjacent normal samples of PDAC patients." (PMID 32701143, 2020). "Based on the UALCAN database, we observed a significant downregulation of ZFP28, ZNF132, ZNF418, ZNF426, ZNF540, and ZNF880 expression levels in primary tumor tissues compared to normal tissues." (PMID 36547193, 2022). "However, the numbers of methylated CG sites in HIST1H4E and ZFP28 were not different between tumor and normal tissues (1.69 ± 1.43 vs. 1.74 ± 1.70, P=0.587 and 1.69 ± 1.37 vs. 1.47 ± 1.35, P=0.73)." (PMID 32701143, 2020).
cancer (1 paper, 2017). A tumor composed of atypical neoplastic, often pleomorphic cells that invade other tissues. "Reciprocally we can observe promoter elements being extinguished in cancer cells as exemplified for ZNF471 and ZFP28 (bottom)." (PMID 28859074, 2017).
ZFP28 also shares sentences with these, for which no sentence is quoted: melanoma (1 paper); Stillbirth (1).